ALK (ALK receptor tyrosine kinase)
Diseases named in the same sentence as ALK in open-access papers (continued):
Sharing a sentence is not in itself a finding about the gene and the disease.
tumor (continued). "The patient’s tumor was tested for the alternative drivers ROS1 and MET that are known to be responsive to some ALK inhibitors but the results were negative." (PMID 28763012, 2017). "Molecular genetic analysis was performed on the previously resected left upper lobe tumour with pyrosequencing showing an EGFR deletion in exon 19 (c.2235_2249del15) and negative IHC for ALK." (PMID 28347348, 2017). "ALK negative ALCL is a genetically and biologically heterogeneous neoplasm previously considered a provisional entity because of the lack of specific biomarker." (PMID 28061468, 2017). "Immunohistochemistry demonstrated that the tumor was negative for S100, CD34, cKit, desmin, and anaplastic lymphoma kinase (ALK), and there was no increase in immunoglobulin (Ig)G4-positive plasma cells." (PMID 26987706, 2016). "In ALK negative ALCL, all tumor cells are positive for CD30, mainly on the cell membrane and in the Golgi region." (PMID 27612448, 2016). "Among the 26 ALK IHC-positive cases, one case contained insufficient tumor cells for FISH, 4 cases failed FISH due to no hybridization signal, and 20 cases showed ALK gene rearrangement positivity by FISH." (PMID 27142166, 2016). "The tumor cells were immunoreactive to CD34, CD99, c-kit, and Bcl-2 and they were negative for CD117 (c-kit), anaplastic lymphoma kinase (ALK-1), smooth muscle actin, desmin, cytokeratin, and S100 protein." (PMID 27795866, 2016). "Using this sample with 35 % viable tumor tissue, the patient was found to be both EGFR wild-type and ALK-negative by FISH." (PMID 27480287, 2016). "In some cases, tumor cells infiltrate lymphatic sinuses and consist of CD30 positive large cells predominantly, which result in difficulty of distinguishing it from ALK negative ALCL." (PMID 27612448, 2016). "Select tumor samples were evaluated by ISH for MET TOP2A, and ALK, with no genetic aberrations (i.e. amplification or rearrangement) detected." (PMID 26498363, 2015). "Recent studies on IMTs have identified clonal abnormalities of the anaplastic lymphoma kinase (ALK) gene, but the impact of this feature on the neoplastic behavior of the tumor is not clarified." (PMID 25767734, 2015). "There are limited numbers of studies on ALK CNG and survival outcome, and not much has been studied on the relationship between ALK CNG and tumor behavior as yet." (PMID 25803816, 2015). "With alterations in the anaplastic lymphoma kinase (ALK) gene and an overexpression of ALK protein reported in many cases of IMT, the concept that IMT is a true neoplasm, rather than a reactive process, has been increasingly accepted." (PMID 25789060, 2015). "The immunohistochemical staining showed that the tumor cells of the large area were negative for CD117, DOG1, desmin, ALK, CD21, CD23, and S100 protein and showed focal positivity for smooth muscle actin." (PMID 26445324, 2015). "The release of GzB into the cytosol would be predicted to be particularly detrimental in ALK+ ALCL, as tumour cells in ALK+ ALCL patient samples do not express the GzB inhibitor, proteinase inhibitor-9 (PI-9)." (PMID 25168906, 2014). "Our findings demonstrate that ALK rearrangements tended to be present in NSCLC patients with no smoking habit, younger age and tumor stage IV." (PMID 24959902, 2014). "Taken together, our findings demonstrate that ALK rearrangements tended to be present in NSCLC patients with no smoking habit, younger age and tumor stage IV." (PMID 24959902, 2014). "Stable expression of ALK-wt or gain-of-function mutants in NCPC were sufficient to induce formation of highly aggressive and undifferentiated tumors, but not to drive NB tumor progression." (PMID 24947326, 2014). "Tumour cells were negative for broad-spectrum cytokeratin, epithelial membrane antigen, S100, MelanA, CD34, CD117, DOG-1 and anaplastic lymphoma kinase (ALK)-1." (PMID 25481247, 2014).
tumor (continued). "The most notable finding of this study was that ALK rearrangements tended to be present in NSCLC patients with no smoking habit, younger age and tumor stage IV." (PMID 24959902, 2014). "Following ALK CISH, in addition to missing cores or the absence of tumor in the cores, 12 cases were technically unsuccessful (no signal detected), while 2 cases had marked crush artefact resulting in interpretation difficulties." (PMID 25188507, 2014). "In the present case, the tumor cells were positive for vimentin, CD68 and Ki-67, and negative for S-100, SMA, desmin, CD31, CD34, ALK and AE1/AE3." (PMID 24959221, 2014). "The immunohistochemistry staining showed that the tumor cells were diffusely positive for S-100, CD1a, langerin and CD68, but negative for CD3, CD5, CD20, CD21, CD30, CD38, CD56, CD79a, ALK, HMB-45, Melan-A, pan-cytokeratin and MPO." (PMID 23388086, 2013). "The tumor cells showed strong CD30 expression, EMA, Ki-67, and LCA, and negative stain for p80NPM/ALK, CKAE1/AE3, CD20, CD3, CD56, and CD15." (PMID 23840974, 2013). "Immunohistochemically, tumor cells diffusely expressed cytokeratins, vimentin, CD68, CD163, and EMA, with focal expression of SMA, S-100, calponin, and CD3, but were negative for CD21, CD35, CD1a, ALK, and HHV8." (PMID 42311660, 2026). "Immunohistochemically, the tumor cells were diffusely positive for p16 and negative for pancytokeratin, S100, SOX10, CD34, smooth muscle actin (SMA), desmin, epithelial membrane antigen (EMA), anaplastic lymphoma kinase (ALK), CD68, CD117, and DOG1." (PMID 40765583, 2025). "Immunohistochemical staining showed that the tumor cells were widely positive for CD30 but negative for epithelial membrane antigen (EMA), leukocyte common antigen (LCA), anaplastic lymphoma kinase (ALK), CD79a, and CD20." (PMID 41250242, 2025). "A proteogenomic study of 99 never-smoking Korean patients with EGFR- and ALK-wildtype LUAD identified four molecular subgroups with distinct clinical outcomes, based on previously defined tumour and microenvironment signatures applied to transcriptome and proteome data." (PMID 40849356, 2025). "Beyond canonical signaling axes, ALK may engage non-canonical mechanisms, such as aberrant activation of the Hedgehog/SMO-GLI axis, which has been observed in preclinical tumor models and may contribute to tumor stemness and resistance." (PMID 41614760, 2025). "The tumor cells were negative for pan-Trk, ROS1, and anaplastic lymphoma kinase (ALK)." (PMID 40211332, 2025). "The tumor cells are variably positive for CD20 and CD45, and express terminal B-cell differentiation markers such as MUM1, whereas they are negative for CD79alpha, PAX5, CD138, CD30, ALK, CD3 and EBER." (PMID 40869163, 2025). "In the entire analyzed group, the risk of progression was not significantly related to age, gender, ALK or ROS1 abnormality testing method (IHC vs. FISH vs. NGS), body weight, smoking status, size and location of tumor, CNS and bone metastases, or treatment toxicities." (PMID 40227844, 2025). "The tumor cells were negative for SMA, CD34, bcl-2, ALK, and BCOR." (PMID 39857780, 2025). "Immunohistochemically, the tumor cells are positive for MDM2 and CDK4 and negative for ALK." (PMID 40282503, 2025). "Genetic studies have similarly shown that rearrangement of the ALK gene may contribute to tumorigenesis, suggesting that IMT is likely to occur as a tumor entity and is not a reactive progression due to a particular disease." (PMID 38761221, 2024).
tumor (continued). "Main weaknesses include lack of tumor genomic characterization (beyond the absence of activating EGFR and ALK alterations), inclusion of only cytotoxic and antiangiogenic therapies, lack of information on postprogression therapy, and exclusion of squamous tumors." (PMID 38207008, 2024). "ALK rearrangements were more frequent in non-drinkers (5.95% vs. 1.05%, P = 0.047) and patients with advanced stages (6.81% vs. 3.26%, P = 0.025), and RET fusions were more common in patients with normal tumor markers (4.92% vs. 1.35%, P = 0.007)." (PMID 39364008, 2024). "The fusion of ALK and LOC399815 has not been reported in any tumor type." (PMID 38241569, 2024). "The tumor cells were positive for PAX8, weakly and focally positive for CK20, CKAE1/AE3, CD10, and AMACR, and negative for CK7, CD117, MelanA, HMB45, TFE3, Actin, and ALK." (PMID 38892169, 2024). "An important point to note is that diagnosing ALK-negative IMT is challenging due to its markedly variable histomorphology, the absence of a definitive immunoprofile, and a long list of differential diagnoses related to the tumor's location." (PMID 39171208, 2024). "In the same way, ALK and MET oncogenic fusions are not pathognomonic to a specific tumor type." (PMID 39409964, 2024). "ALK‐ and EGFR‐positive NSCLCs have distinct histological profiles, suggesting that their tumor marker profiles may also be different; however, no study to date has compared the tumor marker profile of NSCLCs with different driver gene mutations." (PMID 38400801, 2024). "In addition, the tumor cells were negative for CD30 and CD3, precluding the diagnosis of ALK-positive anaplastic large-cell lymphoma (ALCL)." (PMID 36915094, 2023). "In such instances and in cases in which the tumor cellularity is below 10%, reflexing OFA sNGS and Idylla Genefusion-negative cases for ALK and ROS1 fusion detection by FISH and/or IHC may be necessary." (PMID 37628603, 2023). "However, three SNPs found in genes such as ALK, KDR, and ABL1 in the HBL tumor in this study were not reported in UCSC, COSMIC, and ClinVar databases." (PMID 37273678, 2023). "Regardless of the presence of ALK fusion protein, TYK2 inhibitors can induce tumor cell apoptosis." (PMID 35211406, 2022). "Atezolizumab has been approved as monotherapy for first-line treatment of patients with metastatic NSCLC whose tumors have high PD-L1 expression (either ≥50% of tumor cells or ≥10% of tumor-infiltrating immune cells) and no EGFR alteration or ALK translocation." (PMID 36520426, 2022). "Additionally, survival of EML4-ALK fusion NSCLC was inhibited by anti-PD-1 or ALK inhibitor alone, but synergistic tumor killing effect of ALK inhibitor PD-1 inhibitor was not shown." (PMID 36591504, 2022). "Therefore, to diagnose the IPT variant of FDCS correctly, we must perform extensive immunohistochemical staining and recognize real tumor cells as positive for EBV markers (EBER–ISH, CD21, CD23, or CD35) and negative for IgG4 and ALK." (PMID 36484868, 2022). "Notably, cemiplimab monotherapy is already indicated for use (in the United States and in the European Union) as a first-line therapy for adult patients with NSCLC and high PD-L1 expression (≥50% of tumour cells), but without EGFR, ALK, or ROS1 aberrations." (PMID 35328510, 2022). "Third, we did not test other tumor’s driver genes, such as KRAS, ALK, ROS1, and BRAF." (PMID 35096585, 2021). "Tumor cells were positive for CD3, CD8 (72.7%), CD56, CD103 (60%), granzyme B (81.8%), and TIA-1 (66.7%), while negative for CD20, CD10, PD-1, ALK, and EBER ISH." (PMID 34072328, 2021). "These primary tumor imaging features are not significantly different compared to the ALK+ and ROS1+ NSCLC tumors included in our cohort or compared to prior reports on ALK or ROS1+ tumors." (PMID 32183422, 2020).
tumor (continued). "The intensity of 18F-FDG uptake in ALCL tumours may not be an indicator of treatment response and prognosis because ALK-positive ALCL was always reported to have a better prognosis than ALK-negative ALCL." (PMID 31924270, 2020). "While not specifically linked to ALK amplification, PCB-209 showed moderate sensitivity to crizotinib in vitro; thus, the ALK-inhibitor crizotinib was selected for in vivo PDX validation, which showed no statistically significant slowing of tumor growth versus control (p=0.5)." (PMID 32565715, 2020). "The phase III KEYNOTE-024 trial showed pembrolizumab as new standard first-line treatment in advanced NSCLC with high PD-L1 expression, defined as expression in at least 50% of tumor cells, tumor proportion score (TPS) ≥50%, and absence of EGFR or ALK aberrations." (PMID 31179334, 2019). "While application of precision medicine with therapeutics targeting RTKs yields dramatic responses in LUADs bearing oncogenic EGFR, ALK and ROS1, chronic control or cures have not yet been realized due to the inevitability of acquired resistance leading to tumor relapse." (PMID 29458371, 2018). "The administration of the pembrolizumab molecule as first-line therapy to patients without genomic alterations in the genes EGFR, ALK, ROS1 and BRAF, and for whom 50 % of the tumor cells express PD-L1, has given back IHC a primordial role in the therapeutic care of patients with NSCLC." (PMID 29534030, 2018). "Tumor cells are CD30 positive, ALK, TIA-1 and granzyme B negative." (PMID 28061468, 2017). "The lack of strong ALK and GFRA2 expression at the protein level highlights the need to validate analysis at the RNA level with appropriate proteomic characterization of the tumor type being studied." (PMID 28871274, 2017). "After 2 months of daily ALK TKI administration, the tumor manifested no response." (PMID 26968843, 2016). "We find that ALK+ and ALK− ALCL share common DNA methylation changes for genes involved in T cell differentiation and immune response, including TCR and CTLA-4, without an ALK-specific impact on tumor DNA methylation in gene promoters." (PMID 27705804, 2016). "In some studies, ALK expression correlates with tumour histology and metastases at presentation, but not with overall survival; others, instead, showed a prognostic significance only in ERMS displaying ALK gene copy number gain." (PMID 27385213, 2016). "The tumour exhibited a CD20+, CD79a+, CD 10+, immunophenotype, Bcl-2 focal positivity, Ki-67 >90% positivity, whereas other markers were negative including CD3, CD45RO, CD15, CD30, ALK and EMA." (PMID 26990772, 2016). "The tumor cells from the two maxillary LGMSs, including the recurrent lesion, were positive for vimentin and fibronectin, and negative for S-100 protein, CD34, EMA, h-caldesmon, ALK, MSA and calponin." (PMID 25624890, 2015). "Tumor cell line derived from this patient was inhibited by 1 μM crizotinib (p < 0.0001, one-way ANOVA test) or to a greater extent with 1 μM entrectinib (p < 0.0001 vs. no ALK inhibitor; p < 0.0001 vs. crizotinib one-way ANOVA test)." (PMID 26172300, 2015). "This tumor is negative for ROS1 and ALK gene rearrangement or protein expression (data not shown)." (PMID 26472021, 2015). "Notably, tumor cells did not express CD20, CD30, CD117, PAX5, ALK, EBV, or HHV-8." (PMID 39944461, 2025). "Additionally, none of the animals treated with a combination of ALK TKI and lonafarnib showed any signs of toxicity and all the animals in the combination treatment group were alive at the end of the study without any evidence of a growing tumour mass." (PMID 38653965, 2024). "In our case, ALK analysis was negative by immunochemistry and FISH, and no further molecular analysis could be performed due to lack of optimal amount of tumour cells in the tumour sample for this analysis." (PMID 34801049, 2021).
tumor (continued). "Our results indicate that TFAP2B, ALK and a novel marker OLIG2 may serve as surrogate markers for PAX3/7-FOXO1 status what is especially beneficial in cases where poor quality tumour tissue is not suitable for reliable genetic analyses or shows inconclusive result." (PMID 31493794, 2019). "Similarly, we provide the first demonstration that even in absence of exogenous Myc-ERT activity, ALK-wt, ALK-F1174L, or ALK-R1275Q expression in NCPC JoMa1 are sufficient to initiate highly aggressive, undifferentiated tumor formation, although not to drive NB progression." (PMID 24947326, 2014). "It was revealed on immunohistochemistry that the tumor showed positive immunoreactivity for vimentin, α-smooth muscle actin (α-SMA), and CD68, but was negative for anaplastic lymphoma kinase (ALK), S-100, CD34, CD117, kinesin-like protein-1 (KP-1), myelin basic protein (MBP), and desmin." (PMID 25022487, 2014). "Moreover, ALK- ALCL cases with the TP63 rearrangement (see section on molecular alterations) are positive for p63 by immunohistochemistry and the interpretation of the isolated expression of p63 does not always translate into a tumor with squamous cell differentiation." (PMID 34572893, 2021). "Indeed, the analysis of 16 human ALK+ALCL by double staining for CD30 and the TCRβ chain showed an absence of tumour cells co-expressing both proteins, again suggesting that the presence of a TCR is not compatible with tumour cell survival in the presence of NPM–ALK." (PMID 26753883, 2016). "Similarly, in the initial RAN classifier, attention maps frequently focused on tumor regions with high nuclear density and architectural complexity, suggesting these features may serve as general indicators of fusion positivity across ROS1, ALK, and NTRK subtypes (heatmaps not shown)." (PMID 40739404, 2025).